SENP5 (SUMO specific peptidase 5)
Description:
Protease that catalyzes two essential functions in the SUMO pathway: processing of full-length SUMO3 to its mature form and deconjugation of SUMO2 and SUMO3 from targeted proteins. Has weak proteolytic activity against full-length SUMO1 or SUMO1 conjugates. Required for cell division.
Synonyms: MGC27076
Tractability: PROTAC: ubiquitination databases record sites on it; a small molecule that binds it is known.
Target class: Enzyme; Hydrolase
Gene: Protein-coding gene on chromosome 3 (196,867,856 to 196,934,718, forward strand). Ensembl gene ENSG00000119231.
Subcellular location: Nucleus, nucleolus
Pathways (Reactome):
Metabolism of proteins: SUMO is proteolytically processed
Gene Ontology:
Molecular function: protein binding; SUMO-specific endopeptidase activity; deSUMOylase activity; cysteine-type peptidase activity
Biological process: protein sumoylation; proteolysis
Cellular component: nucleoplasm; nucleolus; postsynaptic cytosol; presynaptic cytosol
Genetic constraint (gnomAD): Loss-of-function variants: 16 observed, 53.03 expected, observed/expected ratio (o/e) 0.3, 90% interval 0.2 to 0.46. The upper end of that interval is the gene's LOEUF score, 0.46, which puts it in group 2 of 6, group 1 being the genes least tolerant of losing a copy. Missense variants: 637 observed, 761.32 expected, observed/expected ratio (o/e) 0.84, 90% interval 0.78 to 0.89. Synonymous variants: 264 observed, 274.63 expected, observed/expected ratio (o/e) 0.96, 90% interval 0.87 to 1.06.
Homologues: Orthologues: chimpanzee SENP5 (99% identical), macaque SENP5 (95% identical), dog SENP5 (90% identical), rabbit SENP5 (89% identical), pig SENP5 (88% identical), rat Senp5 (83% identical), rat Senp5l1 (82% identical), mouse Senp5 (82% identical), guinea pig SENP5 (79% identical), tropical clawed frog senp5 (42% identical), Drosophila melanogaster Ulp1 (15% identical), Caenorhabditis elegans ulp-1 (12% identical), and 1 more. Paralogues in human: SENP3 (25% identical), SENP1 (17% identical), SENP2 (15% identical).
Diseases named in the same sentence as SENP5 in open-access papers:
SENP5 is named in the same sentence as 31 diseases in open-access papers, as found by Europe PMC text mining. Sharing a sentence is not in itself a finding about the gene and the disease. The quoted sentences say what the papers report.
breast carcinoma (8 papers, 2014 to 2025). "According to these findings, low expression of SENP5 is associated with good prognosis among breast cancer patients." (PMID 24658161, 2014). "To elucidate associated mechanisms, we tested the phenotypic effect of SENP5 silencing on breast cancer cell lines." (PMID 24658161, 2014). "High expression of the SENP5 gene is associated with poor prognosis in breast cancer patients." (PMID 34503213, 2021). "This led us to postulate that other factors of breast cancer aggressiveness may be associated with SENP5 activity." (PMID 24658161, 2014). "Database analysis indicates that breast cancer patients with low SENP5 expression have a better prognosis." (PMID 35887358, 2022). "SENP5 has been reported to play critical roles in progression of several cancers including breast cancer, osteosarcoma and OSCC." (PMID 35887358, 2022). "Several studies have focused on the relationship between SENP5 and the development of breast cancer." (PMID 33968766, 2021). "One study showed that SENP5 silencing inhibits breast cancer cell growth, proliferation, migration and invasion by regulating the expression level of TGFβRI." (PMID 33968766, 2021). "Recently, another study showed that the expression levels of SENP5 were negatively correlated with the survival of breast cancer patients, and suggested SENP5 as a unique prognostic biomarker." (PMID 33968766, 2021). "Findings indicate that breast cancer patients with low expression levels of SENP5 have a better prognosis than those with high levels." (PMID 29459674, 2018). "Following these findings, we analyzed SENP5 silencing and show it is followed by inhibition of anchorage-independence growth, proliferation, migration and invasion in breast cancer cell lines." (PMID 24658161, 2014). "Our findings demonstrated a pivotal role of SENP5 in determining prognosis in breast cancer patients, according to their SENP5 expression profiles." (PMID 24658161, 2014). "Our findings highlight a novel, SENP5-dependant mechanism, governing metastasis and prognosis in breast cancer through TGFβ signaling, under a well regulated SUMOylation control." (PMID 24658161, 2014). "Our findings highlight a novel, SENP5-dependant mechanism, clinical research based, governing metastasis and prognosis in breast cancer through TGFβ signaling, under a well regulated SUMOylation control." (PMID 24658161, 2014). "Here, we show that SENP5 silencing leads to inhibition of anchorage-independence growth, proliferation, migration and invasion in breast cancer cell lines." (PMID 24658161, 2014). "To test the phenotypic effects of SENP5 on breast cancer cells, we first examined the proliferation rate of cancer cells transfected with control or SENP5 siRNA (siControl and siSENP5, respectively)." (PMID 24658161, 2014). "Indeed, SENP5 depletion inhibits proliferation, anchorage-independent growth, migration and invasion of breast cancer cells." (PMID 35887358, 2022). "Interestingly, a previous study also demonstrated that SENP5 promotes breast cancer invasion by sustaining the sumoylation of TβRI, whose expression is negatively correlated with the prognosis of breast cancer patients." (PMID 35216622, 2022). "The low expression of SENP5 is correlated with a good prognosis in patients with breast cancer." (PMID 33273928, 2020). "Expression levels of SENP5 negatively correlate with survival of breast cancer patients." (PMID 24658161, 2014). "Here, we observed that SENP5 overexpression significantly enhanced the growth of CAKI-2 cells and breast cancer organoids while exerting minimal effects on lung adenocarcinoma organoids, HepG2, and fetal mouse-derived liver and kidney organoids." (PMID 41268439, 2025). "MMP9 was critical in TGFβ-induced invasion and depletion of SENP5 resulted in a dramatic reduction of MMP9, which indicates that SENP5 regulated the invasion of breast cancer by TGFβ-induced MMP9." (PMID 33273928, 2020).
breast carcinoma (continued). "This is the first report represents SENP5-TGFβ-MMP9 cascade and its mechanistic involvement in breast cancer." (PMID 24658161, 2014). "Dynamic monitoring of spheroid diameters revealed that SENP5 overexpression promoted growth in CAKI-2 cells and breast cancer organoids but had minimal impact on lung adenocarcinoma organoids, HepG2 cells, and fetal mouse-derived liver and kidney organoids (bright-field images)." (PMID 41268439, 2025). "The knockdown of SENP5 in TNBC cells significantly reduces the level of MMP9 and decreases levels of total, phosphorylated, and SUMOylated TGFβRI, which is a stimulator of invasion at later stages of breast cancer." (PMID 34503213, 2021). "We showed that upon SENP5 silencing, proliferation rates were only slightly reduced, with an intriguing lack of impact on proliferation rates in MCF7 and T47D, which are ER+ and are weakly invasive breast cancer cell lines." (PMID 24658161, 2014).
osteosarcoma (5 papers, 2014 to 2024). A usually aggressive malignant bone-forming mesenchymal neoplasm, predominantly affecting adolescents and young adults. "SENP5 is overexpressed in osteosarcoma cells and its depletion causes cell growth inhibition and enhanced apoptosis." (PMID 35887358, 2022). "On the other hand, SENP5 has oncogenic activity in osteosarcoma, both in patients’ primary cancer cells and in cell lines, where this SUMO protease is overexpressed, resulting in resistance to both apoptosis and arrest of the cell cycle." (PMID 38534381, 2024). "The inhibition of osteosarcoma growth following SENP5-knockdown is likely via an increase in caspase-3/-7 activity (apoptosis activators) and a decrease in the expression of the cell cycle gene, cyclin B1." (PMID 36078118, 2022). "Osteosarcoma cells and tissues exhibit SENP5 overexpression, important for cell division and maintenance of mitochondrial morphology and function." (PMID 35465332, 2022). "Silencing SENP5 expression in two osteosarcoma cell lines, U2OS and Saos-2, significantly inhibits growth and colony formation and promotes apoptosis." (PMID 36078118, 2022). "In the present study in osteosarcoma cell lines, it was observed that silencing the expression of SENP5 significantly decreased cell proliferation, which was consistent with the function of SENP5 in cell division." (PMID 24926368, 2014). "The results showed that SENP5 was significantly overexpressed in all osteosarcoma cell lines, compared with HOB cells (human osteoblasts isolated from normal human bone)." (PMID 24926368, 2014). "In combination, these results indicated that SENP5 inhibition decreased osteosarcoma cell proliferation by inducing G2/M arrest and apoptosis." (PMID 24926368, 2014). "SENP5 inhibition suppressed the growth and colony formation capacity of two osteosarcoma cell lines, U2OS and Saos-2." (PMID 24926368, 2014). "In the present study, SENP5 was observed to be overexpressed in osteosarcoma cell lines and tissues." (PMID 24926368, 2014). "The results indicated that SENP5 regulated osteosarcoma cell proliferation by inducing G2/M arrest and apoptosis." (PMID 24926368, 2014). "For example, the desumoylase SENP5 is highly expressed in osteosarcoma cells and tissues." (PMID 36078118, 2022). "SENP5 controls osteosarcoma cell proliferation by regulating G2/M arrest and apoptosis, and therefore could represent a reliable strategy for osteosarcoma treatments." (PMID 35465332, 2022). "The present study showed that SENP5 is overexpressed in osteosarcoma cells." (PMID 24926368, 2014). "The present study aimed to determine SENP5 expression levels in osteosarcoma cell lines." (PMID 24926368, 2014). "Moreover, SENP5 inhibition also resulted in spontaneous osteosarcoma cell apoptosis, when compared with mock inhibition cells." (PMID 24926368, 2014). "In addition, lentivirus-mediated small interfering RNA (siRNA) of SENP5 significantly inhibited cell growth and induced apoptosis in osteosarcoma cells." (PMID 24926368, 2014). "The mechanism of SENP5-depletion-induced G2/M arrest in osteosarcoma cells was also investigated." (PMID 24926368, 2014). "In addition, the effect of lentivirus-mediated siRNA of SENP5 on cell growth and apoptosis in osteosarcoma cells was investigated." (PMID 24926368, 2014). "The results from the present study reveal an indispensable role of SENP5 in the regulation of G2/M arrest and apoptosis in osteosarcoma cells, which supports the hypothesis that SENP5 may be a promising drug target for antiosteosarcoma treatment in the future." (PMID 24926368, 2014). "Thus, the present study reported a role of SENP5 in the regulation of osteosarcoma cell proliferation and apoptosis." (PMID 24926368, 2014). "However, substrates in osteosarcoma cells that are responsible for SENP5-regulated G2/M arrest and apoptosis remain to be identified." (PMID 24926368, 2014). "Western blot was used to detect the protein expression of SENP5 in osteosarcoma cells and tissue." (PMID 24926368, 2014).
osteosarcoma (continued). "Thus, consistently with its activity as an apoptosis inhibitor observed in osteosarcoma, SENP5 mediates resistance to therapy, and on these bases, the inhibition of SENP5 may represent a possible strategy for the disease treatment." (PMID 38534381, 2024).
hepatocellular carcinoma (3 papers, 2019 to 2025). A malignant tumor that arises from hepatocytes. "SENP5 was found upregulated in several types of cancer, including oral squamous cell carcinoma, hepatocellular carcinoma, and polymorphisms observed in non-small cell lung cancer." (PMID 37684630, 2023). "In liver tissue, hepatocellular carcinoma exhibited elevated levels of SUMO1, SUMO2/3, UBC9, and SENP5 compared to normal controls." (PMID 41268439, 2025).
esophageal squamous cell carcinoma (2 papers, 2016 to 2023). Esophageal squamous cell carcinoma (ESCC) is a type of esophageal carcinoma (EC) that can affect any part of the esophagus, but is usually located in the upper or middle third. "SENP5 plays an important role in many cancer types, including esophageal squamous cell carcinoma." (PMID 26901676, 2016).
glioblastoma (2 papers, 2021 to 2025). The most malignant astrocytic tumor (WHO grade IV). "As can be seen from the figure, UBE2I, UBA2, PIAS3, and SENP1 were upregulated in glioblastoma, whereas PIAS1, RANBP2, SENP5, and SENP2 were downregulated in glioblastoma." (PMID 33898460, 2021). "Moreover, UBE2I, UBA2, PIAS3, and SENP1 were highly expressed in glioblastoma, whereas PIAS1, RANBP2, SENP5, and SENP2 were downregulated in glioblastoma." (PMID 33898460, 2021). "PIAS1, RANBP2, SENP5, and SENP2 were downregulated in glioblastoma." (PMID 33898460, 2021).
lung adenocarcinoma (2 papers, 2023 to 2025). A carcinoma that arises from the lung and is characterized by the presence of malignant glandular epithelial cells. "Compared to normal lung tissue, lung adenocarcinoma (LUAC) exhibited highly elevated levels of SUMO1 and SENP5, whereas lung squamous cell carcinoma (SCC) showed increased expression of UBC9, SENP1 and SENP5." (PMID 41268439, 2025).
oral squamous cell carcinoma (2 papers, 2014 to 2023). "SENP5 has been reported to be predominantly localized to the cytoplasm of oral squamous cell carcinoma (OSCC) and is associated with the differentiation of OSCC." (PMID 24926368, 2014). "Expression of SENP5 has been reported in oral squamous cell carcinoma (OSCC) and the protease has been associated with the differentiation of OSCC." (PMID 24926368, 2014).
Zinc deficiency (2 papers, 2020 to 2022). A deficiency of the essential metal Zinc; an essential cofactor for many enzymes. "It was established that zinc deficiency induced SENP5 overexpression, which led to cardiac dysplasia." (PMID 35805904, 2022). "This suggested that SENP5 overexpression, potentiated by zinc deficiency, induces abnormal development of myocardial cells." (PMID 33211757, 2020). "In order to investigate the function of SENP5 in zinc deficiency, hiPSC-CMs were transfected with SENP5 small interfering RNA." (PMID 33211757, 2020). "It was confirmed that zinc deficiency induced abnormal differentiation of hiPSCs and increased apoptosis of hiPSC-CMs by promoting SENP5 overexpression, which led to cardiac dysplasia." (PMID 33211757, 2020). "Zinc deficiency induced abnormal hiPSC differentiation, increased cells apoptosis, and decreased the viability of hiPSC-CMs by inducing SENP5 overexpression, which caused myocardial abnormality." (PMID 33211757, 2020). "According to the previous results, a zinc deficiency induces increased expression of SENP5." (PMID 33211757, 2020). "The effect of zinc deficiency, and relationship to SENP5, was investigated further." (PMID 33211757, 2020). "The results of IHC revealed the expression of SENP5 was increased, whereas the SUMO1 modified proteins was decreased with deficiency of zinc.These results imply that zinc deficiency presented cardiac dysplasia, which maybe associated with overexpression of SENP5 protein." (PMID 33211757, 2020). "Thus, it was concluded that SENP5 regulates the SUMO1 deconjugation during heart development and zinc deficiency may reduce conjugated SUMO by promoting SENP5 overexpression, which induces abnormal development of the myocardium." (PMID 33211757, 2020).
acute kidney injury (1 paper, 2025). Sudden and sustained deterioration of the kidney function characterized by decreased glomerular filtration rate, increased serum creatinine or oliguria. "Analysis of SENP family expression in mouse kidney tissue revealed that the transcriptional levels of SENP3 and SENP5 were significantly elevated in IRI-induced acute kidney injury (IRI-AKI) mice." (PMID 41350286, 2025).
acute myeloid leukemia (1 paper, 2025). Acute myeloid leukemia (AML) is a group of neoplasms arising from precursor cells committed to the myeloid cell-line differentiation. "While SUMOylation has been shown to be an important regulatory mechanism in innate immunity, its specific role in neutrophil function has been limited to linking SUMO protease 5 (SENP5) expression to the neutrophil differentiation of acute myeloid leukemia (AML) cells." (PMID 40732357, 2025).
cardiac ischemia (1 paper, 2019). "Indeed, SENP1, SENP2 and SENP5, as well as SENP3, have each been strongly implicated in cardiac ischemia/reperfusion so it is likely that distinct subsets of SUMOylated proteins are regulated by different SENPs." (PMID 30973885, 2019).
cardiomyopathy (1 paper, 2022). A disease of the heart muscle or myocardium proper. "It was suggested that miR-15b-5p modulates platelet reactivity by targeting SUMO Specific Peptidase 5 (SENP5), a SUMO isopeptidase that is activated in the context of platelet activation, ischemia–reperfusion injury and cardiomyopathy." (PMID 35596173, 2022).
follicular thyroid carcinoma (1 paper, 2025). "In thyroid tissue, papillary thyroid carcinoma (PTC) had increased SUMO1 and SENP5 expression, follicular thyroid carcinoma (FTC) showed higher SUMO1 levels, and undifferentiated thyroid carcinoma (UTC) exhibited elevated SUMO1, SUMO2/3, UBC9 and SENP5 levels." (PMID 41268439, 2025).
gastric cancer (1 paper, 2018). A primary or metastatic malignant neoplasm involving the stomach. "The high expression of OPA1 showed statistically significant with P < 0.05 in both breast and gastric cancer (P = 1.6e-06, respectively); while SENP5 was associated with RFS in the other two cancer types – ovarian cancer (P = 0.011) and gastric cancer (P = 1.1e-05)." (PMID 29459674, 2018).
heart failure (1 paper, 2021). Inability of the heart to pump blood at an adequate rate to meet tissue metabolic requirements. "Studies have shown that the level of SENP5, which mainly deconjugates SUMO2/3, is elevated in heart failure." (PMID 34638970, 2021).
penile squamous cell carcinoma (1 paper, 2021). "As another example, the SENP5-encompassing 3q27.2-q29 region is amplified in 11% of penile squamous cell carcinoma patients, which may indicate enhanced SENP5 activity." (PMID 34503213, 2021).
renal cell carcinoma (1 paper, 2020). "We can see that SENP5, SENP3, UBE2I, PIAS3, TRIM27, SAE1, and CBX4 are risk factors in the development of renal cell carcinoma." (PMID 33123273, 2020).